MIR151A (microRNA 151a)
Synonyms: hsa-mir-151; MIR151; MIRN151; hsa-mir-151a
Gene: MicroRNA gene on chromosome 8 (140,732,564 to 140,732,653, reverse strand). Ensembl gene ENSG00000254324.
Gene Ontology:
Biological process: miRNA-mediated post-transcriptional gene silencing
Homologues: Orthologues: chimpanzee ptr-mir-151 (100% identical), macaque MIR151A (89% identical), pig MIR151A (87% identical), rabbit MIR151A (86% identical), guinea pig MIR151A (69% identical), mouse Mir151 (69% identical), dog MIR151 (57% identical). Paralogues in human: MIR28 (53% identical), MIR151B (31% identical).